NDUFC2 (NADH:ubiquinone oxidoreductase subunit C2)
Description:
Accessory subunit of the mitochondrial membrane respiratory chain NADH dehydrogenase (Complex I), that is believed not to be involved in catalysis but required for the complex assembly. Complex I functions in the transfer of electrons from NADH to the respiratory chain. The immediate electron acceptor for the enzyme is believed to be ubiquinone.
Synonyms: CI-B14.5b; HLC-1; B14.5b; MC1DN36; NADHDH2
Tractability: Small molecule: an approved drug acts on it; a structure with a bound ligand is known. Antibody: its Gene Ontology location is reachable by antibodies, with high confidence; UniProt predicts a signal peptide or a membrane-spanning region. PROTAC: ubiquitination databases record sites on it; its protein half-life has been measured.
Gene: Protein-coding gene on chromosome 11 (78,068,297 to 78,081,871, reverse strand). Ensembl gene ENSG00000151366.
Subcellular location: Mitochondrion inner membrane
Subcellular location (Human Protein Atlas): Mitochondria
Pathways (Reactome):
Metabolism: Complex I biogenesis; Respiratory electron transport
Immune System: Neutrophil degranulation
Gene Ontology:
Molecular function: protein binding; NADH dehydrogenase (ubiquinone) activity
Biological process: mitochondrial respiratory chain complex I assembly; aerobic respiration; mitochondrial electron transport, NADH to ubiquinone; proton motive force-driven mitochondrial ATP synthesis; negative regulation of non-canonical NF-kappaB signal transduction; negative regulation of reactive oxygen species biosynthetic process; positive regulation of ATP biosynthetic process; positive regulation of mitochondrial membrane potential; proton transmembrane transport
Cellular component: cytoplasm; mitochondrial inner membrane; mitochondrion; respiratory chain complex I; azurophil granule membrane; plasma membrane
Genetic constraint (gnomAD): Loss-of-function variants: 2 observed, 6.53 expected, observed/expected ratio (o/e) 0.31, 90% interval 0.12 to 0.96. That is too few expected variants to judge how well the gene tolerates losing a copy. Missense variants: 144 observed, 141.99 expected, observed/expected ratio (o/e) 1.01, 90% interval 0.88 to 1.16. Synonymous variants: 58 observed, 51.68 expected, observed/expected ratio (o/e) 1.12, 90% interval 0.91 to 1.4.
Gene-disease validity (ClinGen):
ClinGen rates the evidence that NDUFC2 causes each of these diseases.
Leigh syndrome (autosomal recessive): Moderate. A progressive neurological disease defined by specific neuropathological features associating brainstem and basal ganglia lesions.
mitochondrial disease (autosomal recessive): Moderate.
Homologues: Orthologues: chimpanzee NDUFC2 (87% identical), macaque NDUFC2 (76% identical), rabbit ALG8 (75% identical), pig NDUFC2 (73% identical), guinea pig NDUFC2 (71% identical), rat Ndufc2 (71% identical), dog NDUFC2 (69% identical), mouse Ndufc2 (67% identical), zebrafish ndufc2 (29% identical), tropical clawed frog ndufc2 (28% identical), Caenorhabditis elegans nduc-2 (26% identical), Drosophila melanogaster ND-B14.5B (18% identical).
Diseases named in the same sentence as NDUFC2 in open-access papers:
NDUFC2 is named in the same sentence as 34 diseases in open-access papers, as found by Europe PMC text mining. Sharing a sentence is not in itself a finding about the gene and the disease. The quoted sentences say what the papers report.
breast carcinoma (4 papers, 2007 to 2023). "Previous studies have shown that NDUFC2 is associated with a worse prognosis in breast cancer and serves as an acute coronary syndrome biomarker, as well as a target for new therapeutic strategies." (PMID 37062830, 2023). "GISTIC identifies a peak encompassing four genes (THRSP, NDUFC2, ALG8 and KCTD21), amplification of which have been shown in breast cancer to correlate with over-expression and poor survival." (PMID 20844748, 2010).
Insulin resistance (3 papers, 2016 to 2025). Increased resistance towards insulin, that is, diminished effectiveness of insulin in reducing blood glucose levels. "NDUFC2 appears to be downregulated in the skeletal muscle cells of individuals with insulin resistance and is linked to insulin secretion in vivo." (PMID 38689208, 2024). "In addition, dysregulation of NDUFC2 has been reported to impair mitochondrial ROS clearance and contribute to insulin resistance." (PMID 40426853, 2025).
acute coronary syndrome (2 papers, 2022 to 2023). Signs and symptoms related to acute ischemia of the myocardium secondary to coronary artery disease. "Furthermore, a significant decrease of NDUFC2 mRNA was detected in peripheral blood mononuclear cells from patients experiencing acute coronary syndrome (ACS)." (PMID 35711349, 2022).
Hypertension (2 papers, 2022 to 2023). The presence of chronic increased pressure in the systemic arterial system. "Additional studies in different cohorts are required to reinforce the current evidence on the contributory role of Ndufc2 deficiency to LVH development in human hypertension." (PMID 37558995, 2023). "We demonstrated for the first time a significant association of NDUFC2 variants with LVH in human hypertension and highlight a key role of Ndufc2 deficiency-dependent CI mitochondrial dysfunction on increased susceptibility to cardiac hypertrophy development." (PMID 37558995, 2023). "Previous evidence highlighted a key role of NDUFC2, a subunit of complex I, deficiency in the increased occurrence of renal and cerebrovascular damage in an animal model of hypertension, and of juvenile ischemic stroke occurrence in humans." (PMID 35711349, 2022). "In-vivo, Ndufc2 silencing may contribute to cause increased cerebral and renal vascular damage in an animal model of hypertension." (PMID 35711349, 2022).
ischemic stroke (2 papers, 2016 to 2021). A stroke disorder caused by obstruction of blood flow to the brain, due to thrombotic (local blood clot formation) or embolic (due to a blood clot or other material traveling from another site) event. "The identification of a marker of the human gene, associated with a significant NDUFC2 defective expression in carriers and with early-onset ischemic stroke occurrence, supports the hypothesis that reduced NDUFC2 expression could contribute to increased stroke susceptibility also in humans." (PMID 27594970, 2016). "A previous study reported that the expression level of NDUFC2 may contribute to the occurrence of ischemic stroke." (PMID 33809961, 2021).
Leigh syndrome (2 papers, 2020). "Here, we describe three affected children from two unrelated families who presented with Leigh syndrome due to homozygous variants (c.346_*7del and c.173A>T p.His58Leu) in NDUFC2, encoding a complex I subunit." (PMID 32969598, 2020). "This work describes the first confirmed pathogenic variants in NDUFC2 in a case of mitochondrial disease presenting with symptoms of Leigh syndrome and a severe deficiency in OXPHOS complex I. NDUFC2 was shown to be important for the assembly of the membrane arm of complex I." (PMID 32969598, 2020).
melanoma (2 papers, 2020 to 2026). A malignant, usually aggressive tumor composed of atypical, neoplastic melanocytes. "CRISPR screening further showed that NARS2 and NDUFC2 are necessary for the proliferation of melanoma cells, highlighting these genes as potential therapeutic targets." (PMID 41636115, 2026).
ovarian carcinoma (2 papers, 2014 to 2024). A malignant neoplasm originating from the surface ovarian epithelium. "PKM2, MRPS12, NDUFC2, HPDL, MRPL14, COA6 and RNF144B were significantly upregulated in ovarian cancer tissues than in normal tissues (P < 0.05), while RPL23, FGFR1OP2, CAPN10, ALDH1L1 and ACSM1 were significantly down-regulated (P < 0.05)." (PMID 39478854, 2024). "PKM2, MRPS12, NDUFC2, HPDL, MRPL14, COA6 and RNF144B were significantly upregulated in ovarian cancer, but the down-regulation of NDUFC2, HPDL, MRPL14, COA6 and RNF144B was associated with poor prognosis in patients with ovarian cancer." (PMID 39478854, 2024).
Parkinson disease (2 papers, 2018 to 2021). A progressive degenerative disorder of the central nervous system characterized by loss of dopamine producing neurons in the substantia nigra and the presence of Lewy bodies in the substantia nigra and locus coeruleus. "NDUFC2, the most significant novel gene from brain tissue, encodes a subunit of the mitochondrial membrane respiratory chain NADH dehydrogenase that is associated with mitochondrial diseases including Parkinson’s disease." (PMID 33809961, 2021).
Stroke (2 papers, 2016 to 2022). Sudden impairment of blood flow to a part of the brain due to occlusion or rupture of an artery to the brain. "NDUFC2 downregulation was first discovered as a contributory mechanism to cerebral and renal vascular damage upon a high-salt Japanese-style diet (JD) in the animal model of stroke-prone spontaneously hypertensive rat (SHRSP)." (PMID 35711349, 2022). "In vivo, a heterozygous Ndufc2-ko rat model, obtained from the parental SHRSR strain, showed a deficient complex I assembly and, more importantly, once fed with the Japanese style diet, developed renal damage followed by stroke occurrence, similarly to what occurs in SHRSP." (PMID 27594970, 2016).
type 2 diabetes (2 papers, 2014 to 2022). "A 6-month training study in males with and without a family history of type 2 diabetes showed decreased DNA methylation of genes with known function in muscle and type 2 diabetes, including MEF2A, RUNX1, NDUFC2, and THADA, decreased after exercise." (PMID 35323665, 2022).
acute myeloid leukemia (1 paper, 2007). Acute myeloid leukemia (AML) is a group of neoplasms arising from precursor cells committed to the myeloid cell-line differentiation. "The genes on cytoband 11q14.1, NDUFC2, ALG8 and USP35, also reside close to what appears to be a novel amplicon in acute myeloid leukemias (AML)." (PMID 17925008, 2007).
cardiac hypertrophy (1 paper, 2023). "Therefore, our data provide further evidence of a biological link underlying the association between NDUFC2, SIRT3 and cardiac hypertrophy." (PMID 37558995, 2023). "The impact of Ndufc2 deficiency on cardiac hypertrophy development has not been investigated yet." (PMID 37558995, 2023).
colorectal carcinoma (1 paper, 2017). A malignant epithelial neoplasm that arises from the colon or rectum and invades through the muscularis mucosa into the submucosa. "The NDUFC2 gene has higher mutation rates and has been recommended as a target candidate for treating colorectal carcinoma tumorigenesis." (PMID 28246402, 2017).
pancreatic cancer (1 paper, 2022). "In this work, we observed that knockout of the NADH dehydrogenase complex subunit genes NDUFB10, NDUFC2, NDUFC2-KCTD14, NDUFS8 led to a decrease in the sensitivity of MIA PaCa-2 pancreatic cancer cells to oxaliplatin." (PMID 35209078, 2022).
papillary thyroid carcinoma (1 paper, 2017). "The NDUFC2 gene also shows lower expression in papillary thyroid carcinoma patients." (PMID 28246402, 2017).
stable angina (1 paper, 2022). "Furthermore, NDUFC2 mRNA level was significantly downregulated, along with a higher degree of mitochondrial structural damage and dysfunction, in ACS compared to stable angina patients." (PMID 35711349, 2022).
type 2 diabetes mellitus (1 paper, 2014). A type of diabetes mellitus that is characterized by insulin resistance or desensitization and increased blood glucose levels. "Because a linked SNP to NDUFC2 altered the susceptibility to glucose-stimulated insulin secretion, a diabetes-related phenotype, we asked whether the NDUFC2 L46V SNP could alter susceptibility to diabetes." (PMID 25245408, 2014).
cancer (6 papers, 2014 to 2022). A tumor composed of atypical neoplastic, often pleomorphic cells that invade other tissues. "Among the differentially expressed genes in metastatic samples, we found 7 of 30 genes (MAPK13, XIAP, AHR, SPN, TER1, EMP2, NDUFC2) were cancer-related." (PMID 28009993, 2017). "In some cases, several genes (e.g., CD274 and NDUFC2) were amplified in two or more datasets that originated from a single cancer subtype." (PMID 24874471, 2014). "NDUFC2-amplified cancer cells may have alterations in mitochondrial energy metabolism, but further work will be necessary to investigate these mechanisms and potential sensitivity to complex I inhibitors." (PMID 24874471, 2014). "The genes encoding the metabolic enzymes for oxidation phosphorylation such as Atp5l, Cox4i1, Cox5a, Cox7a2, Ndufc2, Ndufs4, Sdhd, Uqcrq28 were significantly downregulated in 20(S)/(R)-Rh2E2-treated LLC-1 cancer cells, but not in normal cells." (PMID 32796841, 2020). "DEF8, NDUFC2, GUSBP1, ARIH2, STX12 and HIST1H2BN were highly re-expressed (more than 100 folds) in either treatment of MV4-11, have not been previously discussed on their role in cancer except for HIST1H2BN." (PMID 32337016, 2020).
- tumors (3 papers, 2010 to 2017). "Amplification of 8q24.11-13 (THRAP6, DCC1, SQLE, SPG8) and 11q14.1 (NDUFC2, ALG8, USP35) have been associated with poor prognosis in a novel subtype of high-grade ER- tumors." (PMID 20932292, 2010). "We examined PNMT-, NDUFC2-, and MTAP-associated outlying genes that were part of metabolic pathways and also ERBB2-, PAK1-, and CDKN2A-associated outlying genes that were related to the oncogenic/tumor suppressor pathways." (PMID 23383675, 2012). "The most recurrent frameshift MSI events are found in ACVR2A (51.6% of the tumours), KIAA2018 (51%), SLC22A9 (50%), ASTE1 (45%), TGFBR2 (44%), NDUFC2 (36%), LTN1 (36%) and SEC31A (36%)." (PMID 28585546, 2017).
neurological diseases (2 papers, 2018 to 2019). "NDUFC2 is the first enzyme complex of the mitochondrial electron transport chain and is associated with some neurological disorders." (PMID 31500202, 2019).
neurodegenerative disease (1 paper, 2022). A disorder of the central nervous system characterized by gradual and progressive loss of neural tissue and neurologic function. "Finally, several proteins that are associated with neurodegenerative diseases were upregulated either during isolation (Pfn4, C1qb, Bag5 and Sv2c) or following regrouping (oxidative phosphorylation-associated genes such as Ndufc2)." (PMID 34650208, 2022).
NDUFC2 also shares sentences with these, for which no sentence is quoted: mitochondrial disease (2 papers); Alzheimer disease (1); brain diseases (1); cognitive decline (1); glioblastoma (1); head and neck cancer (1); Huntington disease (1); Infertility (1); ischemic heart disease (1); lung adenocarcinoma (1); lung carcinoma (1); prostate carcinoma (1).